B4GALNT1 (beta-1,4-N-acetyl-galactosaminyltransferase 1)
Diseases named in the same sentence as B4GALNT1 in open-access papers (continued):
Sharing a sentence is not in itself a finding about the gene and the disease.
tumor (continued). "Furthermore, the expression of B4GALNT1 (Beta-1,4-N-Acetyl-Galactosaminyltransferase 1) could potentially contribute to the regulation of the tumor micro-environment (TME) and tumor immunity." (PMID 37296620, 2023). "Moreover, the enzymatic activity of B4GALNT1 also acts as a major role in tumor metastasis: B4GALNT1 is an enzyme essential for the synthesis of gangliosides such as GD2/GM2, which are proven to be highly expressed in various types of tumor tissues compared with their corresponding normal tissues." (PMID 35935585, 2022). "Concerning the mechanisms related to the heterogeneous GD2 expression across tumor entities, the integration of CNA data into our analysis revealed a potential influence of B4GALNT1 amplification on GD2 expression." (PMID 41424948, 2025). "However, how B4GALNT1 regulate tumor progression and tumor immunity remains largely unknown." (PMID 39616302, 2024). "To verify the major B4GALNT1-expressing cell type, we further analyzed the single-cell data of HCC tumor tissues from 9 patients (GSE125449) and 10 other patients (GSE149614)." (PMID 39616302, 2024). "Notably, B4GALNT1 upregulation and CERS4 downregulation correlated with advanced tumor stage and metastasis." (PMID 41666167, 2026). "Our findings pioneer the investigation into the critical role of B4GALNT1 in HCC, especially in the context of tumor progression and immunosuppression, which advances the understanding of HCC pathogenesis and lays the groundwork for developing more precise and personalized treatment plans." (PMID 39616302, 2024). "Our results confirmed that B4GALNT1 depletion significantly reduced tumor weight (p < 0.05), and the absence of B4GALNT1 led to a reduction in CD4 + T cells and CD163 + TAMs." (PMID 39616302, 2024). "Therefore, increased numbers of macrophages and Th2 cells resulting from the upregulation of B4GALNT1 reshape the TME into an immunosuppressive environment, which ultimately promotes tumor progression." (PMID 39616302, 2024). "Similar results were observed in detecting protein and secreted levels of SPP1, demonstrating that B4GALNT1 could promote the synthesis and secretion of SPP1 from tumor cells via HES4." (PMID 39616302, 2024). "Eventually, it is known that B4GALNT1 is a relatively ideal target, but targeting GPC3 and ERBB2 might lead to severe “on-target, off-tumor toxicity” in some tissues." (PMID 34975912, 2021). "Comparison of expression profiles of ET (≤40 years) and LT (≥55 years) yielded few genes that are unique between the two groups, 7 genes B4GALNT1, S100P, KLK4, HIST3H2A, DRD4, PCSK1N, and BAPX1 were significantly overexpressed in early-onset tumours compared to late-onset tumours." (PMID 31292488, 2019). "In the gene correlation analysis, clustering results for genes such as B4GALNT1, SIGLEC10, and PSAP further support the idea that these genes may participate in similar biological processes or pathways, particularly those related to inflammation, immune regulation, and tumor progression." (PMID 41445741, 2025). "In addition, B4GALNT1 expression may play a role in TME and tumor immunity regulation." (PMID 35935585, 2022).
neurological disorders (2 papers, 2020 to 2023). "As expected from KO mice phenotypes of the B4galnt1 gene, the intensity of their neurological disorders was milder than expected." (PMID 32168753, 2020). "Furthermore, it was also indicated that B4galnt1 (GM2 synthase) KO mice lacking GM1 ganglioside showed Parkinson disease-like neurological disorders even in heterozygotes." (PMID 32168753, 2020).
movement disorder (1 paper, 2023). Neurological conditions resulting in abnormal voluntary or involuntary movement, which may impact the speed, fluency, quality and ease of movement. "The homozygous GM3 synthase‐deficient mice are one subject of this study, with focus on movement disorders and defective short‐term spatial memory, which are also present in B4galnt1(−/−) and B4galnt1(+/−) mice." (PMID 37401916, 2023).
B4GALNT1 also shares sentences with these, for which no sentence is quoted: Spastic paraplegia (4 papers); peripheral neuropathy (3); clear cell renal cell carcinoma (2); Cognitive impairment (2); Ataxia (1); autism spectrum disorder (1); cortical atrophy (1); demyelinating disease (1); developmental delay (1); Dysarthria (1); Dystonia (1); embryonal carcinoma (1); endometriosis (1); epilepsy (1); head and neck squamous cell carcinoma (1); immune dysfunction (1); kidney cancer (1); leukemia (1); oral squamous cell carcinoma (1); retinitis pigmentosa (1); systemic lupus erythematosus (1); Troyer syndrome (1).